ID1 (inhibitor of DNA binding 1)
Description:
Transcriptional regulator (lacking a basic DNA binding domain) which negatively regulates the basic helix-loop-helix (bHLH) transcription factors by forming heterodimers and inhibiting their DNA binding and transcriptional activity. Implicated in regulating a variety of cellular processes, including cellular growth, senescence, differentiation, apoptosis, angiogenesis, and neoplastic transformation. Inhibits skeletal muscle and cardiac myocyte differentiation. Regulates the circadian clock by repressing the transcriptional activator activity of the CLOCK-BMAL1 heterodimer (By similarity).
Synonyms: bHLHb24; ID; dJ857M17.1.2
Tractability: PROTAC: ubiquitination databases record sites on it.
Target class: Transcription factor
Gene: Protein-coding gene on chromosome 20 (31,573,014 to 31,606,515, forward strand). Ensembl gene ENSG00000125968.
Subcellular location: Cytoplasm; Nucleus
Subcellular location (Human Protein Atlas): Nucleoplasm
Pathways (Reactome):
Cellular responses to stimuli: Oncogene Induced Senescence
Developmental Biology: Transcriptional and post-translational regulation of MITF-M expression and activity
Signal Transduction: NGF-stimulated transcription
Gene Ontology:
Molecular function: protein binding; transcription regulator inhibitor activity; transcription corepressor activity; protein dimerization activity
Biological process: negative regulation of DNA-templated transcription; negative regulation of transcription by RNA polymerase II; angiogenesis; blood vessel endothelial cell migration; blood vessel morphogenesis; negative regulation of cold-induced thermogenesis; neuron differentiation; transforming growth factor beta receptor signaling pathway; circadian rhythm; positive regulation of gene expression
Cellular component: nucleoplasm; nucleus; cytoplasm
Genetic constraint (gnomAD): Loss-of-function variants: 8 observed, 9.94 expected, observed/expected ratio (o/e) 0.8, 90% interval 0.47 to 1.44. That is too few expected variants to judge how well the gene tolerates losing a copy. Missense variants: 347 observed, 224.73 expected, observed/expected ratio (o/e) 1.54, 90% interval 1.41 to 1.69. Synonymous variants: 176 observed, 105.91 expected, observed/expected ratio (o/e) 1.66, 90% interval 1.47 to 1.88.
Homologues: Orthologues: chimpanzee ID1 (100% identical), macaque ID1 (97% identical), rabbit ID1 (95% identical), guinea pig ID1 (95% identical), dog ID1 (94% identical), pig ID1 (92% identical), mouse Id1 (90% identical), rat Id1 (82% identical), zebrafish id1 (52% identical), Drosophila melanogaster emc (28% identical). Paralogues in human: ID4 (42% identical), ID2 (41% identical), ID3 (32% identical).
Diseases named in the same sentence as ID1 in open-access papers:
ID1 is named in the same sentence as 220 diseases in open-access papers, as found by Europe PMC text mining. Sharing a sentence is not in itself a finding about the gene and the disease. The quoted sentences say what the papers report.
breast carcinoma (130 papers, 2004 to 2025). "Loss of Naa10p resulted in increased ID1 expression and breast cancer cell migration, whereas knockdown of STAT5 demonstrated reduced ID1 gene expression and inhibited cell migration." (PMID 40507264, 2025). "For instance, elevated expression of ID1 is associated with high invasiveness in breast cancer and contributes to the development of hormone-resistant." (PMID 38195969, 2024). "The invasion and metastatic potential of breast cancer have been closely associated with ID1 expression and are needed for the maintenance of cancer stem-like features." (PMID 33917757, 2021). "Surprisingly, ID1 level that is shown by the previous study to be implicated in breast cancer metastasis was noted to be downregulated." (PMID 34869246, 2021). "ID1 has been especially associated with tumor progression and metastasis and is well-studied in breast cancer." (PMID 33917757, 2021). "High levels of Id1 expression in several breast cancer cell lines are associated with high aggressiveness and invasiveness." (PMID 28122577, 2017). "KLF17 can inhibit the transcription of ID1, which is the gene of encoding a key metastasis regulator in breast cancer, via directly binding to its promoter region." (PMID 26662959, 2016). "For example, ATF3-mediated ID1 repression is one of the tumor suppressor arms of TGF-β signaling, but in patient-derived metastatic breast cancer cells TGF-β causes an aberrant increase of ID1 expression promoting lung metastasis." (PMID 26956045, 2016). "When TGFβ induces EMT in breast cancer cells, it also induces ID1 expression, which has been linked to stem-like features of these tumor cells." (PMID 27367735, 2016). "Clinically, higher Id1 level is positively associated with poor patient outcome, high tumor stage, aggressiveness and metastasis in human breast cancer." (PMID 25938540, 2015). "Consistent with this, previous studies showed that high expression of Id1 was linked to EMT-related basal B breast cancer cell lines and the claudin-low tumor subtype, as well as triple-negative breast cancer." (PMID 25938540, 2015). "The Id1 gene encoding a transcriptional regulator and its expression in breast cancer cells has a significant impact on the ability of breast cancer cells to metastasize to the lungs in xenograft models." (PMID 25598217, 2015). "In breast cancer, silencing both Id1 and Id3 caused a significantly greater reduction in tumor initiation and lung colonization than knockdown of either Id1 or Id3 alone." (PMID 23593444, 2013). "ID1 promoter regulation is lost in aggressive breast cancer cells, Id1 is associated with induction of cell proliferation and invasion, and stable antisense targeting of Id1 represses an aggressive and metastatic phenotype in mammary epithelial cells." (PMID 21955753, 2011). "Overexpression of Id1 promotes invasion, proliferation and migration in vitro and high Id1 expression is associated with the metastatic phenotype of breast cancer cell lines in vivo." (PMID 20689821, 2010). "By means of this analysis, we were able to prove that E6/E7 of HPV types 16, 18, 31, 33 and 35 are present in the majority of invasive breast cancer tissues; and their presence is associated with Id-1 overexpression." (PMID 18648363, 2008). "In this study, we investigated the relation between high-risk HPVs and Id-1 expression in breast cancer tissues from Syrian women." (PMID 18648363, 2008). "Among these members, ID1 has been implicated in EMT in breast cancer; the involvement of ID3 in EMT remains unclear." (PMID 39256881, 2024). "Finally, the antimetastatic effect on breast cancer cells demonstrated for CBD in a mouse model was directly linked to a downregulation of Id-1 in a later work." (PMID 35277658, 2022).
breast carcinoma (continued). "Others have also observed an inverse correlation in ID1 and ID2 expression in patients’ chronic myelogenous leukemia (CML) and blast crisis cells and in nonhematopoietic tissue, where loss of ID2 expression and overexpression of ID1 promote colon and breast cancer." (PMID 35775482, 2022). "Id1 has been associated with breast cancer progression in a number of studies." (PMID 21955753, 2011). "In another approach, Henke and coworkers developed an anti‐tumour agent that downregulates ID1 effectively in tumour ECs, which yielded a significant reduction in breast cancer growth and metastasis." (PMID 40116596, 2025). "In breast cancer, Id1 was identified as the only transcription factor within a set of genes associated with high risk of lung metastasis." (PMID 41303422, 2025). "RhoC appears to be the main protein responsible for the invasion and metastasis of breast cancer, and its downregulation is suppressed the migratory and invasive phenotype induced by Id1." (PMID 41303422, 2025). "Knockdown of Id1 and Id3, either individually or in combination, from a cell line representative of the TN human subgroup of breast cancer resulted in partial or complete inhibition of the tumor-initiating capacity, respectively." (PMID 41303422, 2025). "A monospecific monoclonal antibody revealed positive staining for Id1 in 36% of TN (triple-negative) breast cancers." (PMID 41303422, 2025). "ID1 has been identified as the most important gene for the Normal-like subtype and the second most important gene across all other breast cancer subtypes." (PMID 40468582, 2025). "Investigation of the gene expression profile during the early stages of VM formation by MDA‐MB‐231‐LM2 breast cancer cells identified the transcriptional regulator inhibitor of DNA binding 1 (ID1) to be elevated ~ 10‐fold within the first 2 hours." (PMID 40116596, 2025). "Patients with breast cancer who had lymph node metastases typically contained a high expression level of ID1 and low levels of KLF17." (PMID 38195969, 2024). "A study showed that CBD endocannabinoid decreases breast cancer aggressiveness by downregulating the helix–loop–helix protein Id-1, an inhibitor of basic helix–loop–helix transcription factors that promote human breast cancer progression." (PMID 38672512, 2024). "Recent studies on breast cancer (BC) have revealed a bidirectional regulation between IGF2 and the inhibitor of DNA-binding 1 (Id1) that is linked to cell stemness." (PMID 36672737, 2023). "In this study, we uncover a novel role of ZNF148 in suppressing TNBC cell growth and metastasis and provide evidence for a direct regulatory circuitry between MYC, ZNF148, and ID1/3 that impacts stem cell traits in breast cancer." (PMID 36207293, 2022). "Herein, we provide evidence for a direct transcriptional circuitry that functionally incorporates MYC, ZNF148, and ID1/3, regulating cancer stem cell traits in breast cancer." (PMID 36207293, 2022). "Inhibition of ID1 expression suppresses invasion and metastases in aggressive salivary and breast cancer." (PMID 34295890, 2021). "Significantly decreased Id-1 expression in metastatic breast cancer cells, leading to the downregulation of tumor aggressiveness." (PMID 34834237, 2021). "Id3, often in concert with Id1, is essential for the self-renewal of tumor-initiating cells in several malignancies including glioma, breast cancer, and colon cancer." (PMID 34785704, 2021). "CBD has also been shown to downregulate Id-1 in the aggressive human breast cancer line MDA-MB-231 through modulation of ERK and ROS pathways leading to a decrease in Id-1 expression and also upregulated Id-2 (a transcriptional regulator)." (PMID 34259916, 2021). "Promotion of breast cancer was attributed to the ability of Id-1 to expand the mammary stem cell pool while repressing differentiation." (PMID 34736527, 2021).
breast carcinoma (continued). "These are, however, linked to a reduced expression of the inhibitor of differentiation 1 (Id1) protein, which inhibits basic helix-turn-helix transcription factors and is a key regulator of metastatic potential in breast cancer." (PMID 33383838, 2020). "One study reported that CBD treatment reduced advanced-stage breast cancer metastasis via the downregulation of Inhibitor of DNA binding protein 1 (Id1), a transcriptional factor." (PMID 32708138, 2020). "Benezra and colleagues showed that during metastatic colonization, inhibitor of differentiation 1 (Id1), enhances breast cancer cells' stem-like phenotype by suppressing Twist1 and inducing an MET." (PMID 32391382, 2020). "In breast cancer, Id-1 overexpression has been found to be highly correlated with the ability of primary human breast cancer cells to metastasize to the lung." (PMID 32708138, 2020). "Another study also showed that CBD treatment was able to reduce proliferation and invasion of breast cancer cells via reducing the expression of Id-1." (PMID 32708138, 2020). "Studies by our group and others have already reported that Id1 marks a chemoresistant breast cancer cell in cancers such as hepatocarcinomas, and the Kif11 pathway has been targeted in the treatment of docetaxel-resistant TNBC cells." (PMID 32911668, 2020). "We have previously demonstrated that Id1 cooperates with activated Ras signaling and promotes mammary tumor initiation and metastasis in vivo by supporting long-term self-renewal and proliferative capacity." (PMID 32766238, 2020). "Suppression of invasion and metastasis in aggressive salivary and breast cancer cells is targeted through inhibition of ID1 expression." (PMID 30899759, 2019). "CBD also inhibits the invasiveness of aggressive MDA-MB-231 and MDA-MB-436 breast cancer cell lines by downregulating inhibitor of DNA binding 1 (ID-1), a transcriptional regulator, which stimulates the metastasis of breast cancer." (PMID 30987191, 2019). "A previous study suggested that the TGF-β/ID1 signaling pathway contributes to the stem-like phenotype and promotes the metastatic colonization of breast cancer cells." (PMID 31296250, 2019). "The same group also demonstrated that in breast cancer cells VDR regulation of the inhibitor of differentiation 1 (ID1) expression is mechanistically conserved in tumors." (PMID 30641860, 2019). "Microenvironment-induced plasticity was observed in some genes, such as Id1, that were upregulated in metastases, but then reverted to levels observed in the parental mammary tumors when liver metastases were collected and regrown in the mammary gland." (PMID 30841919, 2019). "Tocotrienols are found to be very effective in human breast cancer cells and for inducing apoptosis in estrogen-responsive and estrogen-nonresponsive human breast cancer cells by targeting cancer cells by inhibiting Id1, a key cancer-promoting protein." (PMID 29606130, 2018). "In a recent study of breast cancer, ID1 was shown to be expressed in tumor cells that had already undergone an EMT, and it contributed to the growth of the primary tumor by inducing a stem cell-like phenotype." (PMID 29376829, 2018). "Id1-overexpressing human breast cancer cells (HMLE) showed high tumor-initiating capacity (TIC) and E-cadherin without Vimentin expression (MET)." (PMID 30463358, 2018). "KLF17 inhibits epithelial-mesenchymal transition (EMT) and invasion of breast cancer cells, and KLF17 protein directly inhibits the transcription of Id1, the key regulator of the metastasis of breast cancer." (PMID 28454121, 2017). "High levels of Id1 and the membrane-type 1-MMP (MT1-MMP) or MMP1 have been associated to breast cancer metastasis." (PMID 28122577, 2017). "Overexpression of ID1 facilitates the G1 to S phase transition, and induces breast cancer metastasis." (PMID 29202775, 2017).
breast carcinoma (continued). "For instance, in breast cancer, another independent study reported both ID1 and ID2 overexpression were related to the advanced tumor stage, shorter OS and disease free survival." (PMID 29190891, 2017). "In contrary, ERβ1 has been identified as a novel binding partner and inhibitor of Id1, which supports ERβ1-induced E-cadherin expression, resulting in the inhibition of the migration and invasion of breast cancer cells." (PMID 28122577, 2017). "Contrarily to Id1, Id2 is down-regulated in aggressive and invasive breast carcinomas, while it is up-regulated in differentiated breast cancer cells." (PMID 28122577, 2017). "Id-1 has been reported to be upregulated and identified as a potential tumor promoter in diverse cancers, including hepatocellular carcinoma and breast cancer." (PMID 29233161, 2017). "For example, by treating human metastatic breast cancer cells with an Id1 antisense oligonucleotide not only Id1 decreases, but also MT1-MMP." (PMID 28122577, 2017). "ID1 was shown to be involved in mesenchymal-to-epithelial transition (MET) of breast cancer cells during lung colonization after having undergone TGF-β-induced EMT." (PMID 28445989, 2017). "Upon metastatic dissemination in recipient mice, the metastatic breast cancer cells require ID1 to inactivate the transcriptional activity of Twist1 before MET can occur." (PMID 27367735, 2016). "In our study, we found that Bcl-3 regulated breast cancerpulmonary metastasis in breast cancer cells by modulating TGFβsignaling via the stabilization of Smad3 and other metastasis-related proteinssuch as ID1 (see discussion below)." (PMID 27906182, 2016). "As expected, epithelial genes known to be inactivated during EMT in breast cancer cells, such as Cdh1 (E-cadherin), Ocln (Occludin), Epcam, Cldn7 (Claudin 7), Id1, Krt7, Esr1, Cav2, Dsp, Gata3, and Cadm1 were among the downregulated genes." (PMID 25674539, 2015). "Collectively, these findings provide in vivo genetic evidence of Id1 functions as an oncogene in breast cancer and indicate that Id1 regulates mammary basal stem cells by activating the Wnt/c-Myc pathway, thereby contributing to breast tumor development." (PMID 25938540, 2015). "Despite the importance of Id1 in mammary development and breast cancer progression, its effect on stemness and differentiation in mammary epithelial cells and its association with mammary tumorigenesis remain to be further elucidated." (PMID 25938540, 2015). "Consistent with the observation in MMTV-Id1 mice, Id1 was more strongly expressed in basal-type breast cancer cell lines." (PMID 25938540, 2015). "Previous studies on breast cancer demonstrated that Id1 and Id3 promote malignant progression by inhibiting apoptosis of cancer cells." (PMID 25061504, 2014). "Id1 plays oncogenic roles in inhibiting cellular senescence and maintaining stemness and also in tumor re-initiation during breast cancer metastasis to the lung." (PMID 24485087, 2014). "Stankic and colleagues have identified a role for the inhibitor of differentiation protein, ID1, as a critical regulator of breast cancer stem-like properties and metastatic colonization." (PMID 25927844, 2014). "ID1 is overexpressed in aggressive triple-negative breast tumors and is required for the metastasis of breast cancer in experimental models." (PMID 25927844, 2014). "The complex context-dependent function of ID1 allows breast cancer cells to retain their EMT-CSC-like mesenchymal phenotype during tumor initiation and metastatic dissemination, and to re-acquire their epithelial character necessary for lung colonization." (PMID 25927844, 2014). "Although further studies are required, our present observations on the E47 and ID1 expression profile in the N0 breast carcinoma series provide biological basis to the interplay between E47 and ID1 here described." (PMID 23555842, 2013).